USF2 (upstream transcription factor 2, c-fos interacting)
Diseases named in the same sentence as USF2 in open-access papers (continued):
Sharing a sentence is not in itself a finding about the gene and the disease.
Alzheimer disease (1 paper, 2022). A progressive, neurodegenerative disease characterized by loss of function and death of nerve cells in several areas of the brain leading to loss of cognitive function such as memory and language. "USF1 and USF2 generally exert activating effects, with USF1 being a risk gene for Alzheimer’s disease and relevant for brain cholesterol metabolism involving its transport from astrocytes to neurons." (PMID 35886042, 2022).
bladder cancer (1 paper, 2025). "Our analysis revealed that several inflammation-associated gene signatures are significantly enriched in patients exhibiting low USF2-NuRD complex scores alongside high Metab-GS scores (Red), suggesting that Metab-GS is associated with inflammatory tumor environment in bladder cancer." (PMID 40626022, 2025). "On the other hand, different tumor progression-related gene signatures were enriched in patients having low USF2-NuRD complex scores and high Metab-GS scores (Blue) suggesting that Metab-GS is associated with tumor aggressiveness and progression in bladder cancer." (PMID 40626022, 2025). "In addition, high USF2 expression was associated with better survival in bladder cancer patients." (PMID 40626022, 2025). "Lastly, oncogenic metabolic hubs in bladder cancer were negatively correlated with USF2-NuRD complex scores whereas positively correlated with HDAC1/2 target scores." (PMID 40626022, 2025). "To this end, we looked for TFs in ChEA3 tool, and found USF2 as top predicted transcription factor regulating oncogenic metabolic hubs in bladder cancer." (PMID 40626022, 2025). "Interestingly, USF2 expression was downregulated in aggressive disease state and genes upregulated in bladder cancer were enriched in patients having low USF2 expression." (PMID 40626022, 2025). "Moreover, bladder cancer-related genes were also enriched in tumors having low USF2-NurRD complex scores compared to those having high USF2-NuRD complex scores." (PMID 40626022, 2025). "Data from Cistrome_DB also showed higher USF2 binding scores to oncogenic metabolic hubs, but these scores were minimal to none for tumor suppressor metabolic hubs in bladder cancer suggesting USF2 as key transcription factor to regulate oncogenic metabolic hubs in bladder cancer." (PMID 40626022, 2025). "Based on these interesting finding, we hypothesized that whatif USF2 downregulates oncogenic metabolic hubs in bladder cancer." (PMID 40626022, 2025). "Overall, these findings suggest that USF2 regulated the expression of oncogenic metabolic hubs in bladder cancer via NuRD-complex driven histone deacetylation, and its downregulation leads to aggressive disease state and poor survival in bladder cancer patients." (PMID 40626022, 2025).
bladder tumors (1 paper, 2025). "We next investigated whether the USF2-NuRD complex/Metab-GS axis correlates with the inflammatory landscape of aggressive bladder tumors." (PMID 40626022, 2025).
colon cancers (1 paper, 2020). "A previous study indicated that USF2 is associated with tumor grade and inversely with survival in Stage II colon cancers." (PMID 32812032, 2020).
endometritis (1 paper, 2022). An acute or chronic, usually bacterial infectious process affecting the endometrium. "This study aims at identifying the effects and interaction of TREM1 and upstream stimulatory factor 2 (USF2) in endometritis by using a model of lipopolysaccharide (LPS)-induced human endometrial epithelial cells (HEnEpCs)." (PMID 35100093, 2022). "Collectively, USF2 promotes endometritis by upregulating TREM1, thereby activating TLR2/4-NF-κB pathway." (PMID 35100093, 2022). "It caught our interest in that there are studies implying that USF2 overexpression may regulate downstream cytokines in endometritis." (PMID 35100093, 2022). "We thus hypothesized that USF2 might transcriptionally regulate TREM1 expression in endometritis." (PMID 35100093, 2022). "Therefore, we presumed that USF2 might transcriptionally activate TREM1 to promote endometritis." (PMID 35100093, 2022). "In the present study, an in vitro model of LPS-induced human endometrial epithelial cells (HEnEpCs) was established to investigate whether USF2 can induce transcriptional activation of TREM1 and promote endometritis by regulating TLR2/4-NF-κB signaling pathway." (PMID 35100093, 2022).
Hepatic steatosis (1 paper, 2022). Steatosis is a term used to denote lipid accumulation within hepatocytes. "This is consistent with our previous finding that hepatic steatosis was 3-fold higher in First Nation adolescents with T2D compared to normoglycemic controls, although whether methylation of the USF2 promoter is a contributing factor remains to be investigated." (PMID 36303872, 2022).
hyperplasia (1 paper, 2015). An abnormal increase in the number of cells in an organ or a tissue with consequent enlargement. "A recent study with USF2–/– mice revealed that male USF2–/– mice display dysregulated prostate growth and marked prostate hyperplasia already at a young age." (PMID 25741280, 2015).
Hypertension (1 paper, 2013). The presence of chronic increased pressure in the systemic arterial system. "Recently, the E-boxes in the promoter regions of renin and angiotensinogen were shown to be direct targets of Usf1 and Usf2 and suggested to be involved in the pathogenesis of both hypertension and renal injury." (PMID 23653383, 2013).
iron overload (1 paper, 2023). "USF2 is associated with iron overload and regulates hepcidin expression, which increases in the LV remote region after MI." (PMID 36197585, 2023).
liver cirrhosis (1 paper, 2014). "USF1 and USF2 expressions were increased in patients with liver cirrhosis, worse tissue differentiation, advanced HCC stages and metastatic recurrence." (PMID 25149140, 2014). "USF1 and USF2 protein expressions were significantly increased in patients with liver cirrhosis, worse tissue differentiation, advanced HCC stages, high-tendency to metastatic recurrence and postoperative metastatic recurrence (P < 0.05)." (PMID 25149140, 2014). "Furthermore, we also found that both USF1 and USF2 expressions were significantly increased in patients with liver cirrhosis, poor differentiation, advanced tumor stages, the high-tendency to metastatic recurrence and postoperative metastatic recurrence." (PMID 25149140, 2014).
lymphoma (1 paper, 2025). A malignant (clonal) proliferation of B- lymphocytes or T- lymphocytes which involves the lymph nodes, bone marrow and/or extranodal sites.
neuroblastoma (1 paper, 2013). Neuroblastoma (NB) is the most common solid, extracranial childhood tumor. "A few are unique to human neuroblastoma nuclear extracts, specifically Pax4a, USF2, and BTEB2." (PMID 23368879, 2013).
promyelocytic leukemia (1 paper, 2016). "In addition, arsenic trioxide (ATO) was found to repress the expression of NF-κB (and other transcription factors namely Sp1, c-Myc and Upstream Transcription Factor 2 (USF2)) in human promyelocytic leukemia cells and reduce the transcription of hTERT." (PMID 27548225, 2016).
Ureteral obstruction (1 paper, 2013). Obstruction of the flow of urine through the ureter. "Furthermore, the results of siRNA transfection in mouse distal convoluted tubule cells and those of unilateral ureteral obstruction in the afflicted mouse kidney suggest that Usf1 decreases but Usf2 increases the Agtrap gene expression by binding to the E-box." (PMID 23653383, 2013).
tumor (26 papers, 2014 to 2025). "Further functional studies were required to elucidate the mechanisms by which RUNX1 and USF2 impact fibroblast subpopulations and tumor biology." (PMID 39870619, 2025). "Restoring miR-10a-5p levels in these cells decreased USF2 expression, reduced cell proliferation, and enhanced apoptosis, thereby confirming the tumor-suppressive role of miR-10a-5p in CML." (PMID 39796267, 2025). "In CML, reduced miR-10a-5p levels led to the overexpression of oncogene USF2, thereby promoting tumor growth." (PMID 39796267, 2025). "Multi-plex IHC confirmed co-localization of RUNX1 with FAP protein at the tumor core and USF2 with PDGFRA expression at the tumor margin." (PMID 39870619, 2025). "USF2 deficiency induces reactive oxygen species formation and contributes to the activation of the ERK1/2-AKT pathway, thereby promoting tumor proliferation and migration." (PMID 37564208, 2023). "We found that a decreased expression of USF2 in HCC tumor tissues compared with adjacent normal liver tissues." (PMID 36319631, 2022). "USF2 plays an important role in various cellular processes, especially in the genesis and progression of tumours." (PMID 35255935, 2022). "The result showed that the protein levels of TXNRD1 and phospho-Akt were consistently higher in HCC tumor tissues compared with their adjacent normal tissues, while a consistently opposite expression pattern of USF2 was detected." (PMID 36319631, 2022). "In conclusion, the results of the present study on the effect of TGF-β1 on 90K transcription and the role of USF1 and USF2 in the regulation of 90K gene expression have uncovered a novel possible role for 90K in the TGF-β1-driven tumor progression program." (PMID 33888686, 2021). "The data demonstrated that only USF1, YY1, STAT3 and USF2 were up-regulated in the three OS tumor samples when compared with paired normal specimens." (PMID 32269179, 2020). "The top TFs found to negatively regulate the expression of cell cycle genes (SMAD5, IKZF1, USF1, USF2) have been previously shown to have a role as transcriptional repressors and as inhibitors of cellular proliferation in tumor cell lines." (PMID 28899340, 2017). "Some studies support the idea of GSK3β and USF2 being tumor suppressive, other studies show a cancer promoting effect." (PMID 25741280, 2015). "Both USF1 and USF2 are supposed to have major roles in metabolism, tissue protection and tumor development." (PMID 25741280, 2015). "The upstream stimulatory factor 2 (USF2) is a regulator of important cellular processes and is supposed to have also a role during tumor development." (PMID 25238393, 2014). "USF1 and USF2 were also found to be up-regulated in primary HCC tumor tissues (all P < 0.001, respectively)." (PMID 25149140, 2014). "This mechanistic insight is particularly compelling, as it suggests that modulating the activity of USF2 or the NuRD complex may restore the balance between oncogenic and tumor suppressor metabolic pathways, thereby impeding tumor growth." (PMID 40626022, 2025). "However, classic studies had established USF2 as a regulator of the cell cycle and tumor suppression." (PMID 37097016, 2023). "USF2 functioned as tumor suppressor through the downstream repression of TXNRD1." (PMID 36319631, 2022). "Furthermore, the nude mice injected with shUSF2-transfected HLF cells were found have larger tumor volume and tumor weight than those injected with control cells, while this enhancement by knockdown of USF2 was blocked by knockdown of TXNRD1." (PMID 36319631, 2022). "Furthermore, the overall survival period was significantly longer in USF2 higher expression group than that in USF2 lower expression group, suggesting a tumor suppressive role and prognostic value of USF2 in HCC." (PMID 36319631, 2022). "Interestingly, the data with respect to the role of USF2 in tumor development are conflicting suggesting that it has a dual role as either tumor promoter or suppressor." (PMID 36319631, 2022).
tumor (continued). "Another possible explanation is that targeted genes whose expression is regulated by USF2 may be more important in determining the tumor-suppressive or tumor-promotive functions of USF2." (PMID 36319631, 2022). "However, the role of USF2 in different tumours is contradictory, suggesting that it is either a tumour promoter or an inhibitor." (PMID 35255935, 2022). "Interestingly, USF2 has been proven to have a dual function as either tumor-suppressor or tumor-promoter." (PMID 34116677, 2021). "Furthermore, through gene expression profiling interactive analysis (GEPIA), we found that the gene expression of USF2 was positively related to RAD17 or NELFA in multiple tumours." (PMID 31845510, 2020). "Interestingly, USF2 has been reported to have a dual role as either tumor-suppressor or tumor-promoter." (PMID 31013770, 2019). "The transcription factor USF2 is supposed to have an important role in tumor development." (PMID 31013770, 2019). "Contrarily, USF2-targeted genes were associated with stress response and cell survival, which may prevent malignant transformation and ECM resolution caused by inflammatory stimuli, such as stress or aging, to restrain tumor growth." (PMID 39870619, 2025). "Thus, whether USF2 acts as a tumor suppressor or tumor promoter may depend on the regulatory mechanisms involved." (PMID 31013770, 2019). "However, it is almost unknown which regulatory mechanisms contribute to the complex, yet not completely understood, tumor-suppressive or tumor-promoting function of USF2." (PMID 31013770, 2019). "Furthermore, USF2 seems to be linked to cellular transformation and tumor progression, although a concise view has not been reached due to different results." (PMID 31013770, 2019). "We also determined the protein expression of TXNRD1, USF2, and phospho-Akt in paired HCC tumor tissues." (PMID 36319631, 2022). "Here, we identified TXNRD1 as a tumor promoter that stimulates HCC proliferation and metastasis through activating AKT/mTOR signaling, and Upstream transcription factor 2 (USF2) was a major transcriptional repressor of TXNRD1 expression." (PMID 36319631, 2022). "Other studies reported the axis of syntaxin 6/USF2/LC3B which promoted autophagy flux and tumour progression in HCC, showing that syntaxin 6 could trigger autophagy and affect the RACK1/STAT3 axis." (PMID 40293576, 2025). "Importantly, in tumor samples, the expression levels of LGALS3BP showed a direct correlation with those of TGF-β1 (R = 0.34, p < 0.001), USF1 (R = 0.30, p < 0.001), and USF2 (R = 0.37, p < 0.001)." (PMID 33888686, 2021). "For instance, EGR1 and USF2 were highly co-expressed in the tumor sample (scLink’s correlation = 0.77, P = 0.01) but not in the normal sample." (PMID 34252628, 2021). "Moreover, upstream stimulatory factor 2 (USF2) negatively regulates lipid peroxidation and ferroptosis in PC cells by modulating PKM2-mediated transcriptional activity in the nucleus, further promoting tumor progression." (PMID 41169372, 2025).
cancer (19 papers, 2009 to 2025). A tumor composed of atypical neoplastic, often pleomorphic cells that invade other tissues. "USF1 and USF2 were among the first mammalian transcription factors identified and have long been linked to cancer." (PMID 40658711, 2025). "Cyclin-dependent kinase 5 (CDK5) seems to be of importance since high levels of CDK5 were found in different cancers associated with high USF2 expression." (PMID 31013770, 2019). "In this study, we explored the CDK5-mediated phosphorylation of USF2 as a regulatory mechanism, which can cause functional alterations of USF2 in cancer." (PMID 31013770, 2019). "Furthermore, USF2 seems to be linked to the development of cancer." (PMID 25238393, 2014). "DRIM was thought to relate to the metastatic potential and act as a putative nuclear protein regulating certain gene expression in some cancer cells, and that transcription expression in cancer cells is activated by a transcription factor USF2." (PMID 39648301, 2025). "USF2 has been reported to implicate in several cellular processes, such as embryogenesis, metabolism and cancer development." (PMID 36319631, 2022). "USF2 is observed in various human cancers, plays important roles in embryogenesis, metabolism, and cancer development." (PMID 32812032, 2020). "In our study, USF2 exhibited copy number amplification in a variety of cancers according to the TCGA database." (PMID 31845510, 2020). "Collectively, these results establish a novel mechanism by which USF2 protein levels, and hence its function, can be regulated in cancer cells." (PMID 31013770, 2019). "The CDK5-mediated USF2 phosphorylation promotes USF2 protein stability at least in three different cancer cell lines—PC3, HepG2, and MDA-MB-231." (PMID 31013770, 2019). "Together, these data suggest that phosphorylation of USF2 by CDK5 can promote cancer cell proliferation and migration." (PMID 31013770, 2019). "USF2 as a transcription factor plays important roles in processes, such as embryogenesis, metabolism and cancer development." (PMID 31013770, 2019). "Given the lack of evidence regarding the trans-activation effects of EGR1 and USF2 on the SIRT1 promoter in cancer, we focused on investigating the trans-activation effects of these two transcription factors." (PMID 31068761, 2019). "In summary, more studies on the regulation of the transcription factor USF2 are necessary to understand the mechanisms by which it affects the development of different types of cancer." (PMID 25741280, 2015). "These novel findings on the regulation of the transcription factor USF2 set the basis for further studies investigating how these mechanisms contribute to the development of different types of cancer." (PMID 25238393, 2014). "Analyzing the clinical cancer and normal samples from the mouth has shown that the level of expression of USF1 and USF2 is lower in the cancer samples, but the hTERT expression and telomerase activity is higher in the cancer samples." (PMID 22649586, 2009). "Moreover, in cancer cell lines, RAD51 is associated with the regulation of the autophagy pathway and works together with E-box proteins such as USF1, USF2, and MITF to regulate the expression of autophagy-related genes." (PMID 40746357, 2025). "The contribution of GSK3β and USF2 to carcinogenesis also seems to be influenced by the cellular context, although the majority of studies point to a cancer-promoting effect where, like in the present study, GSK3β activated USF2 promoted proliferation and cell migration." (PMID 31013770, 2019). "USF2 is observed in various human cancers but what mechanisms cancer cells could use to suppress or activate its function is largely unknown." (PMID 31013770, 2019).